MIS12 (MIS12 kinetochore complex component)
Description:
Part of the MIS12 complex which is required for normal chromosome alignment and segregation and for kinetochore formation during mitosis. Essential for proper kinetochore microtubule attachments.
Synonyms: MGC2488; hMIS12; KNTC2AP; MTW1; 2510025F08Rik
Tractability: PROTAC: ubiquitination databases record sites on it; its protein half-life has been measured.
Gene: Protein-coding gene on chromosome 17 (5,486,285 to 5,490,816, forward strand). Ensembl gene ENSG00000167842.
Subcellular location: Chromosome, centromere, kinetochore
Pathways (Reactome):
Cell Cycle: Amplification of signal from unattached kinetochores via a MAD2 inhibitory signal; EML4 and NUDC in mitotic spindle formation; Mitotic Prometaphase; Resolution of Sister Chromatid Cohesion; Separation of Sister Chromatids
Signal Transduction: RHO GTPases Activate Formins
Gene Ontology:
Molecular function: protein binding
Biological process: attachment of mitotic spindle microtubules to kinetochore; chromosome segregation; kinetochore assembly; attachment of spindle microtubules to kinetochore; mitotic sister chromatid segregation; mitotic cell cycle
Cellular component: kinetochore; MIS12/MIND type complex; nucleus; outer kinetochore; cytosol; spindle pole; chromosome, centromeric region
Genetic constraint (gnomAD): Loss-of-function variants: 13 observed, 17.52 expected, observed/expected ratio (o/e) 0.74, 90% interval 0.48 to 1.18. The upper end of that interval is the gene's LOEUF score, 1.18, which puts it in group 5 of 6, group 1 being the genes least tolerant of losing a copy. Missense variants: 199 observed, 252.22 expected, observed/expected ratio (o/e) 0.79, 90% interval 0.7 to 0.89. Synonymous variants: 97 observed, 92.67 expected, observed/expected ratio (o/e) 1.05, 90% interval 0.89 to 1.24.
Homologues: Orthologues: chimpanzee MIS12 (100% identical), macaque MIS12 (99% identical), pig MIS12 (90% identical), rabbit MIS12 (87% identical), dog MIS12 (84% identical), rat Mis12 (81% identical), mouse Mis12 (79% identical), tropical clawed frog mis12 (55% identical), zebrafish mis12 (37% identical).
Diseases named in the same sentence as MIS12 in open-access papers:
MIS12 is named in the same sentence as 9 diseases in open-access papers, as found by Europe PMC text mining. Sharing a sentence is not in itself a finding about the gene and the disease. The quoted sentences say what the papers report.
colon cancer (1 paper, 2019). "The inhibitory effect of BITC on the proliferation of human colon cancer HCT-116 cells was consistently suppressed by the overexpression of Mis12, a human orthologue of Mtw1, and enhanced by the knockdown of Mis12." (PMID 31222108, 2019). "In human colon cancer HCT-116 cells, we examined the effects of the overexpression and knockdown of Mis12 on the antiproliferation by BITC." (PMID 31222108, 2019). "We found that the down-regulation of Mis12, a human orthologue of Mtw1, plays an important role in the antiproliferation by BITC in human colon cancer HCT-116 cells." (PMID 31222108, 2019).
Werner syndrome (1 paper, 2024). "In MSCs presenting pathogenic mutations of (HGPS) or Werner syndrome (WS), the MIS12 is downregulated." (PMID 39273655, 2024).
cancer (5 papers, 2015 to 2022). A tumor composed of atypical neoplastic, often pleomorphic cells that invade other tissues. "Although the agents targeting the components of kinetochore complex including Ndc80 and Nuf2 have been shown to have anti-cancer effects, this is the first report, to the best of our knowledge, to show the mechanism to suppress cancer cell proliferation through the degradation of Mis12." (PMID 31222108, 2019). "Our data indicated that the proteasome-dependent decrease in Mis12 induces G2/M delay and enhances the BITC-induced apoptosis, which contributes to the suppression of cancer cell proliferation by BITC." (PMID 31222108, 2019).
MIS12 also shares sentences with these, for which no sentence is quoted: tumor (2 papers); breast carcinoma (1); infection (1); ovarian carcinoma (1); pancreatic cancer (1); renal carcinoma (1).